GAS5 (growth arrest specific 5)
Diseases named in the same sentence as GAS5 in open-access papers (continued):
Sharing a sentence is not in itself a finding about the gene and the disease.
tumor (continued). "Moreover, GAS5 could enhance effects of gemcitabine on suppression of tumor growth and metastasis." (PMID 34368145, 2021). "Upregulation of GAS5 promoted SOCS3 expression and suppressed cell growth, metastasis, and gemcitabine resistance by inhibiting the EMT and tumor stem cell accumulation both in vivo and in vitro." (PMID 34760707, 2021). "Low GAS5 levels were positively correlated with NSCLC characteristics including TNM, tumor size and lymphatic metastasis." (PMID 33418541, 2021). "On the other hand, LINC01111, LINC01963, DGCR5, MEG3, GAS5, and LINC00261 are among tumor suppressor lncRNAs in this tissue." (PMID 34827663, 2021). "In NSCLC, inhibition of GAS5 expression resulted in chemoresistance due to the competition between GAS5 and PTEN for miR-21 binding, regarding the tumor-suppressor activity of PTEN as a negative regulator of the AKT/PKB signaling pathway." (PMID 34771549, 2021). "On the other hand, GAS5 and TP73-AS1 have tumor suppressor activities, the former being down- and the latter up-regulated in TRA VL." (PMID 33546468, 2021). "GAS5 negatively regulates miR‐32‐5p expression, which promotes the expression of PTEN, a well‐known tumour suppressor." (PMID 34405957, 2021). "For example, GAS5 acts as a ceRNA by sponging miR-21 and upregulates the expression of miR-21 targets programmed cell death 4 (PCDC4) and PTEN, both of which are tumor-suppressor genes." (PMID 32486413, 2020). "Overexpression of GAS5 inhibits PDAC cell proliferation, migration and gemcitabine resistance through miR-221/suppressor of cytokine signaling 3 (SOCS3) mediated EMT and tumor CSCs." (PMID 32257946, 2020). "As a confirmed target gene of miR-21, PTEN is involved in the interaction between GAS5 and miR-21.GAS5 can counteract the reduction of PTEN by miR-21, and play a synergistic role in tumor-suppression with PTEN." (PMID 32194641, 2020). "After mouse xenografting, lncRNAs have also been shown to influence the size and weight of the tumor, some replicating the same scenario as in patients, such as AB073614, EPB41L4A-AS2, GAS5, KCNQ1OT1, LINC00565, TINCR and TPT1-AS1." (PMID 32326249, 2020). "Recent studies have shown that lncRNAs have important functions in modulating various tumor progression in HCC, such as growth arrest-specific 5 (GAS5), nuclear-enriched autosomal transcript 1(NEAT1), and taurine upregulated gene 1 (TUG1)." (PMID 32295144, 2020). "GAS5 inhibits cell proliferation also through the miR-544/RUNX3 pathway, where it stimulates NK cell activity and inhibits tumor growth." (PMID 33076450, 2020). "Growth arrest-specific 5 lncRNA (GAS5) is a repressor of glucocorticoid receptor expression, which serves as a tumor suppressor in many cancers." (PMID 32462404, 2020). "Other lncRNAs, including Growth Arrest Specific 5 (GAS5), Maternally Expressed Gene 3 (MEG3), and LOC285194 have been reported to function as tumor suppressors in cancers." (PMID 32943987, 2020). "LncRNA GAS5, which is lowly expressed in CRC tumor tissues and plays a tumor suppressive effect, was highly expressed in CRC samples in the presdent study without reaching a significant difference in all pairs of samples." (PMID 32016349, 2020). "Significantly, lower GAS5 expression was observed in female patients with BLCA and larger tumor sizes than in patients with smaller tumor sizes (p = 0.041)." (PMID 32354045, 2020). "In cells of a granulosa-like tumor cell line (KGN), overexpression of GAS5 led to upregulated IL-6, while silencing of GAS5 played an opposite role." (PMID 33308258, 2020). "lncRNA GAS5 functions as a tumor suppressor in HCC metastasis through directly interacting with miR-182 and low level of GAS5 correlates with poor outcomes." (PMID 32015685, 2020). "Growth arrest-specific transcript 5 (GAS5), which was originally isolated from mouse NIH 3T3 cells by subtractive hybridization, plays various tumor-suppressive roles in several cancers, including those of the breast, stomach, prostate, and lung." (PMID 32413995, 2020).
tumor (continued). "For instance, H19, HOTAIR, MALAT1, TUG1, GAS5, and CCAT1, were found to play important roles in tumor initiation and development 44-49." (PMID 32922554, 2020). "Growth arrest-specific transcript 5 (GAS5) was first confirmed in mouse NIH 3T3 cells and identified as a possible tumor suppressor genes in many cancers." (PMID 31182630, 2019). "GAS5 is involved in growth control and apoptosis and its expression is predominantly identified in quiescent MPM tumor cells." (PMID 31212997, 2019). "Another group showed that the lncRNA GAS5 is downregulated in ovarian cancer, and works to inhibit miRNA-196a-5p, which in turn down-regulates HOXA5 that acts as a tumour suppressor in this context." (PMID 31382546, 2019). "In contrast, YTHDF3 knockdown reversed YAP-mediated promotion of CRC tumor progression, and co-transfection of YTHDF3 and GAS5 also obtained similar results." (PMID 31619268, 2019). "Actually, numerous lncRNAs function as oncogenes or tumor-suppressor genes, which were reported to be involved in metastasis and prognosis of HCC, such as MEG3, GAS5, HOTAIR, HULC, H19, and MALAT1." (PMID 31500187, 2019). "Studies have revealed that AATBC, ADAMTSL4-AS1, EPB41L4A-AS1, MIA-RAB4B, MIR4697HG, GAS5, SNHG12, MSX2P1, and LINC00852 are related to tumorigenesis and tumor progression in multiple cancers, such as bladder, breast, colorectal, and ovarian." (PMID 31850068, 2019). "Apart from oncogenic lncRNA signatures, our study samples also exhibited overexpression of some tumor suppressor lncRNAs (PTENP1-AS and GAS5)." (PMID 29719612, 2018). "Over-expression of Gas5 remarkably suppressed PTC cells proliferation in vitro and inhibited the growth of tumor cells in vivo likewise." (PMID 29423063, 2018). "The lncRNA GAS5 was significantly down-regulated in NSCLC tissues and cell lines; MEG3, which was identified to be up-regulated and played as a tumor suppressor gene in a lot of tumors." (PMID 29899163, 2018). "In this study, we verified the tumor suppressive role of Gas5 as a ceRNA in PTC to modulate PTEN level and identified miR-222-3p as the specific miRNA decoyed by Gas5." (PMID 29423063, 2018). "Over-expression of Gas5 significantly inhibited cell proliferation ability in vitro and in vivo manifested by MTT, colony formation assays and tumor formation assays." (PMID 29423063, 2018). "Expression of the seven lncRNAs UCA1, MALAT1, H19, GAS5, TUG1, ncRAN (SNHG16) and linc-UBC1 (BLACAT) was measured by RT-qPCR in UC tissue set 1 consisting of 106 tumor tissues and 10 benign tissues obtained from radical cystectomies." (PMID 28430799, 2017). "GAS5 is a multi-functional lncRNA in CRC cells as it induces cell cycle arrest and tumor cell apoptosis by enhancing the G1 cell cycle through the cyclin-dependent kinase 6 (CDK6) pathway." (PMID 28392501, 2017). "Herein, it was concluded that the adverse effect of GAS5 on PC metastasis was, at least in part, mediated by the PTEN-induced tumor-suppressor pathway." (PMID 29225772, 2017). "Here we demonstrate that growth-arrest-specific transcript 5 (GAS5), a known tumour suppressor and growth arrest-related lncRNA, is highly expressed and directly regulated by pluripotency factors OCT4 and SOX2 in hESCs." (PMID 27811843, 2016). "Wu and colleagues find that lncRNA growth arrest-specific transcript 5 (GAS5), a tumor suppressor, acts as a microRNA (miRNA) sponge for miR-21 to upregulate expression of phosphatase and tensin homologs (PTEN), a tumor suppressor." (PMID 27897214, 2016). "We also found that GAS5 increased NODAL expression, while reducing the expression of its targeting miRNAs in these tumours." (PMID 27811843, 2016).
tumor (continued). "Several of the detected differentially expressed lncRNAs were well described members of cancer-related pathways, including tumor suppressors and oncogenes (e.g. MEG3, Xist, MALAT1, H19, GAS5, and HOTAIR)." (PMID 25264628, 2014). "In contrast, other studies found that GAS5 increases the cytotoxicity of NK cells against HCC cells and inhibits macrophage M2 polarization—via the miR‐544/RUNX3 axis and PTEN, respectively—thus enhancing anti‐tumor immune function." (PMID 41474641, 2026). "Finally, GAS5 influence over PI3K/AKT culminates in preserving the level of PTEN, a tumor suppressor itself that switches off the PI3K downstream signal and restricts cell proliferation." (PMID 41489907, 2026). "Intriguingly, GAS5 has been reported to be upregulated in exosomes derived from colorectal cancer patients, although it has been reported to be downregulated in exosomes derived from the sera of NSCLC patients and in tumor mouse models." (PMID 40429961, 2025). "Conversely, tumor-suppressor lncRNAs like MEG3 and GAS5 can enhance pro-apoptotic signaling." (PMID 41020820, 2025). "Furthermore, overexpression of GAS5 sensitizes resistant NSCLC cells to EGFR-TKIs and inhibits tumor growth in mice treated with gefitinib." (PMID 38200584, 2024). "In addition, reports have shown that GAS5 interacts with some proteins, such as E2F1, E2F4, YBX1, EZH2, and YAP, which inhibit tumor progression." (PMID 38782769, 2024). "The in vitro and in vivo evaluation of GAS5 impact on CRC progression demonstrated that GAS5 overexpression could suppress CRC cell proliferation, invasion, and it decreases tumor growth." (PMID 38226210, 2024). "GBM sections derived from the patient who was non-tolerant to adjuvant therapy (P2) showed preferential GAS5 expression in these hypoxic regions compared to its expression in more structurally intact tumor cells (39% increase; P2)." (PMID 38258133, 2024). "Major tumor suppressor lncRNAs in GBM are RAMP2-AS1, GAS5 and CASC2." (PMID 38059120, 2024). "In a similar manner, GAS5 sponges miR-106a-5p to finally induce higher levels of p-AKT and p-mTOR in GC cells, which results in a rise of cell proliferation, migration, and invasion, and decline of apoptosis on in vitro models and greater tumor growth in vivo." (PMID 37047267, 2023). "GAS5 is a lncRNA described as a tumor suppressor and is negatively regulated in several cancers, such as bladder, liver, gastric, kidney, cervical, and PCa." (PMID 37047296, 2023). "The clinical significance of GAS5 expression alteration under VRB treatment, is that it may render NSCLC cell subpopulations within the same tumor resistant towards VRB under repetitive exposure." (PMID 38137519, 2023). "In addition, tumor volume and weight were higher in mice that had been treated with 7721/sora-RBM38-OE + GAS5-KD cells than in control mice." (PMID 37296859, 2023). "Although this study did not explore a mechanism for GAS5-mediated tumor suppression, other studies implicate a role for GAS5 as a miRNA sponge to negatively influence cell cycle activator genes or positively influence PTEN levels." (PMID 37370745, 2023). "The results demonstrated that the expression of anti‐tumour lncRNAs DICER‐AS1, TUG1, GAS5 and LINC01121 was significantly increased by 50 μM resveratrol in combination with H19 knockdown, while expression of MALAT1 in cells was significantly downregulated by the combined treatment." (PMID 35166018, 2022). "The levels of GAS5 and NEF in the cancer tissues and serum of ESCC patients are significantly lower than those in normal individuals, and the levels of GAS5 and NEF also decrease with an increase in tumor stage." (PMID 35241975, 2022).
tumor (continued). "Growth arrest specific 5 (GAS5) is a long intergenic non-coding RNA (lincRNA) that has been shown to regulate the cell cycle in various systems, and its high expression inhibits tumor progression of several cancer types." (PMID 34439281, 2021). "Indeed, overexpression of GAS5 promoted apoptosis by decreasing the expression of the anti-apoptosis protein BCL-2 and inhibited tumor resistance to therapy in bladder and cervical cancers." (PMID 33483590, 2021). "Nevertheless, the genotypes of GAS5 SNP rs145204276 did not influence the status of clinical stage, tumor size, lymph node invasion or distal metastasis (all p > 0.05)." (PMID 33925911, 2021). "In addition, low levels of GAS5 expression had a shorter survival time compared to those with high levels and correlated with advanced TNM stages and larger tumor size." (PMID 34571795, 2021). "GAS5 directly interacts with the WW domain of YAP to promote the transfer of endogenous YAP from the nucleus to the cytoplasm, as well as its phosphorylation and its subsequent ubiquitin-mediated degradation which leads to tumor suppression." (PMID 34938735, 2021). "lncRNA GAS5 is involved in the inhibition of tumor progression in different cancer types such as CRC, non-small-cell lung carcinoma (NSCLC), low-grade gliomas, and GC." (PMID 33522932, 2021). "Moreover, the GAS5 SNP rs145204276 variants (Ins/Del or Del/Del) in the non-alcohol-drinking population were associated with significantly advanced tumor stage (OR: 1.500, 95% CI: 1.081–2.081, p = 0.015) and larger tumor size (OR: 1.494, 95% CI: 1.076–2.074, p = 0.016)." (PMID 33925911, 2021). "Furthermore, a piRNA derived from Growth Arrest Specific 5 (GAS5), a tumor-suppressive long non-coding RNA, potently up-regulated the transcription of TRAIL by inducing H3K4 methylation/H3K27 demethylation." (PMID 34282054, 2021). "Clinically relevant analysis showed that patients aged young, with small tumor size and adenocarcinoma, in low tumor stage, as well as without lymph node metastasis had higher GAS5 levels and lower miR‐21 levels." (PMID 32069387, 2020). "In BRCA, lncRNAs are emerging as master regulators in tumor biology, and have oncogenic and tumor suppressor functions related to initiation and cancer progression, some examples are HOTAIR, MALAT-1, lincRNAp21, and GAS5." (PMID 32753692, 2020). "Besides, GAS5 low expression contributes to resistance to gefitinib to LUAD cell lines and tumor tissues." (PMID 32438606, 2020). "Besides, in NSCLC tumor tissues and cell lines (A549, H1299, H1975, HCC827), GAS5 can deregulate the expression of phospho-EGFR, phospho-MAPK1, phospho-AKT1, and IGF1R." (PMID 32438606, 2020). "The proposed mechanism for the tumor suppressor function of GAS5 in this scenario involves the GREM out-competing the DNA-based GRE in the cIAP2 gene, and thus driving the cell toward apoptosis when GAS5 expression is high." (PMID 31533355, 2019). "Tumor suppressive lncRNAs (GAS5, MEG3, FER1L4 and LINC00672) and oncogenic lncRNAs (CCAT2, BANCR, NEAT1, MALAT1, H19 and Linc-RoR) have been identified as key regulators of the established tumor suppressor or oncogenic pathways in EC." (PMID 30781521, 2019). "To further identify the relationship between GAS5 expression and overall survival of LGG patients, we first examined GAS5 expression in LGG patients with different IDH1 status, histologic grades, tumour sizes, and histologic types." (PMID 30853980, 2019). "SNHG2, known as GAS5, is a tumor suppressor gene that has been thoroughly studied previously." (PMID 31691514, 2019). "GAS5 expression was significantly down-regulated in clinical pathology specimens, and there was a significant negative correlation with tumor size, lymph node metastasis, and clinical stage." (PMID 30606744, 2019).
tumor (continued). "For example, by interacting with miRNAs, several lncRNAs (including GAS5, XIST, NORAD, and Linc00511) modulate PC progression by enhancing the proliferation, migration and invasive capacity and angiogenesis of PC cells as well as tumor growth in vivo." (PMID 31488171, 2019). "Therefore, our findings and those of previous studies suggest that GAS5 knockdown-induced G1/S progression occurs via STAT3-mediated signaling pathways, and further suggest that reduced GAS5 expression contributes to tumor progression in MM patients." (PMID 30569211, 2019). "Ultimately, we established a key role of YTHDF3 in m6A-modified GAS5 and degradation of GAS5 transcription, uncovering a negative feedback loop between YAP-interacting lncRNA GAS5 and the m6A reader YTHDF3 in Hippo/YAP signaling and tumor progression of CRC." (PMID 31619268, 2019). "The lncRNA growth arrest-specific transcript 5 (GAS5) is a non-protein coding RNA that is considered a tumor suppressor gene." (PMID 29748618, 2018). "Overexpression of tumor suppressor lncRNAs PTENP1-AS and GAS5 might, in turn, reduce the oncogenic role of miR-21." (PMID 29719612, 2018). "Total RNA was extracted from the tumor tissues and RT-qPCR illustrated that GA decreased EZH2 mRNA expression and increased miR-101 expression, but these effects were significantly suppressed by knockdown of GAS5." (PMID 29445179, 2018). "Reduced GAS5 levels in muscle-invasive tumours, while not statistically significant, were also observed in 63.6% of the MIBC (T2–T4) patients (p = 0.181)." (PMID 30374124, 2018). "RCC patients had a lower GAS5 level and a higher miR-34a level in tumor tissue compared to adjacent non-cancer tissue." (PMID 30289954, 2018). "Focusing on NMIBC, significantly downregulated GAS5 levels detected in HG compared to LG TaT1 tumours (p = 0.006; not shown) and mainly to T1HG (p = 0.006)." (PMID 30374124, 2018). "We next used in situ hybridization to analyze the expression status of GAS5 in mouse tumor tissues and saw that GAS5 expression was notably higher in tumor tissues from corylin-treated mice in comparison with those from the control group (DMSO only)." (PMID 29382035, 2018). "A small-sized tumor diameter and early TNM staging resulted in a higher Gas5 expression." (PMID 29308053, 2018). "Unfortunately, the analysis of GAS5 tumour levels did not highlight a statistically significant prognostic value for the OS of the MIBC patients." (PMID 30374124, 2018). "Amongst them, TUG1 and linc-ROR were not detectable in plasma, ZFAS1 was significantly up-regulated in plasma of tumor patients, while GAS5 showed no significant changes." (PMID 29559565, 2018). "Gas5 mRNA and protein expression was not correlated to age, gender, tumor site, tumor differentiation or lymph node metastasis (P > 0.05)." (PMID 29308053, 2018). "Accordingly, the expression of GAS5-007 in 14 tumor tissue samples was higher than that in 11 normal tissue samples." (PMID 28771526, 2017). "GAS5 was then transferred into OSCC cells and its roles were investigated in tumor progression." (PMID 29296179, 2017). "Growth arrest-specific transcript 5 (GAS5), another downregulated non-coding RNA, is involved in cellular proliferation, and its downregulation has been shown to be pro-cancerous in several tumor types." (PMID 28681241, 2017). "The growth arrest-specific transcript 5 (GAS5) has been brought under the spotlight in recent studies, suggesting it may have pivotal roles in various kinds of tumor." (PMID 28771526, 2017). "GAS5, a prominent non-protein coding RNA gene, is down-regulated in a wide variety of cancer cells and tumor tissues, and has been ascribed tumor suppressor functions." (PMID 29029523, 2017). "By injecting stably transfected hESCs into the backs of nude mice, we found that GAS5-overexpressing hESCs formed larger teratomas than control cells, while mutant GAS5-overexpressng cells did not form significantly larger tumours." (PMID 27811843, 2016).